TLR4 (toll like receptor 4)
Diseases named in the same sentence as TLR4 in open-access papers (continued):
Sharing a sentence is not in itself a finding about the gene and the disease.
cancer (continued). "Third, TLR4 activation has been associated with resistance to chemotherapy in various cancers, including HCC." (PMID 37896221, 2023). "We next examined the associations of TLR4 expression with 8 immune checkpoints (PD-L1, CTLA4, HAVCR2, LAG3, PDCD1, PDCD1LG2, SIGLEC15, and TIGIT), and TLR4 expression was widely associated with the 8 immune checkpoints in most cancer types." (PMID 37576399, 2023). "TLR-4 activation can contribute to the activation of cancer-associated fibroblasts (CAFs) and the development of fibrosis in the GC microenvironment." (PMID 38090147, 2023). "Inflammation and cancer progression have been associated with the Toll-like receptor 4 (TLR4) signaling pathway." (PMID 37637038, 2023). "Gut microbial imbalance can lead to increased LPS, which binds to TLR4 to activate NF-κB, mediates the transcription of stress-related compounds, and increases cancer risk." (PMID 37764869, 2023). "TLR-4 activation can also induce a dysfunction of the immune microenvironment, favoring cancer progression and being associated with worse patient survival in different solid tumors." (PMID 36838231, 2023). "The dimerization of PD-L1 or TLR-4 can cause changes in T-cell activity, making them a potential target for cancer immunotherapy." (PMID 37103820, 2023). "TLR4+ cells are characterized by a more mesenchymal- and cancer stem cell (CSC)-like phenotype, which predisposes to more aggressive disease, as indicated by the higher incidence of microvascular invasion in clinical specimens." (PMID 37345131, 2023). "Long-term activation of TLR4 has been associated with autoimmune-related diseases, neurodegeneration, and cancers." (PMID 36355111, 2022). "Two molecules with a key role in both cancer-associated inflammatory response and immune suppression are toll-like receptor 4 (TLR4) and signal transducer and activator of transcription protein 3 (STAT3)." (PMID 35205801, 2022). "All these findings suggest the critical role of the TLR-4/MD-2 complex in inflammation-associated cancers, which can be interrupted by CAPE." (PMID 36142391, 2022). "Meanwhile, many of the cancer-causing bacteria in the gut promote intestinal tumorigenesis by inducing hyperactivation of the TLR4 signaling pathway." (PMID 34914638, 2022). "One observational study suggested that Fusobacterium, which was found in much higher levels in cancerous tissue as compared to control tissue, increases cancer risk by increasing inflammatory mediators through a possible miRNA-mediated activation of TLR2/TLR4." (PMID 35807903, 2022). "Research on TLR4 has been relatively advanced, including the association of TLR4 with cancer and the molecular mechanism of the TLR4 gene causing cancer." (PMID 36281200, 2022). "Meta-analysis using 22 case-control studies indicated that these TLR4 polymorphisms were associated with increased cancer risk." (PMID 36231099, 2022). "At present, there are few studies on the correlation between TLR4 rs11536891 polymorphism and cancer susceptibility." (PMID 33585082, 2021). "Polymorphisms in the TLR4 allele in humans have been linked to the cancer susceptibility and resistance, depending on the type of cancer studied." (PMID 34771569, 2021). "In various types of cancer, deregulation of TLR4 is closely associated with tumourigenesis and cancer progression." (PMID 34502140, 2021). "The intestinal venous congestion caused by liver graft injury facilitated cancer recurrence by TLR4 increase in rodent models." (PMID 33990548, 2021). "Another vital aspect of this study is that the TLR4 gene is associated with different levels of immune infiltration in cancers (KIRC, SKCM, STAD, TGCT, and UCEC), and this is further associated with OS." (PMID 34631699, 2021). "The association between the expression of the TLR4 gene across cancers and prognosis is based on an analysis of public databases." (PMID 34631699, 2021).
cancer (continued). "In recent years, activation of the TLR4-MyD88-NF-κB signaling pathway has been linked to cancer progression and chemotherapeutic drug resistance." (PMID 34867331, 2021). "Loss of TLR‐4 function in cancer patients has been associated with a rapid relapse after chemotherapy than the patients with normal TLR4 expression." (PMID 32797726, 2020). "More importantly, these p62-deficient cancer cells, including p62KO A549 cells, showed enhanced migration and invasion in response to TLR4 stimulation." (PMID 32384667, 2020). "Taken together, these results suggest that p62 is negatively implicated in the activation of autophagy by TLR4 signaling, thereby demonstrating an involvement in cancer cell invasiveness facilitated by autophagy induction." (PMID 32384667, 2020). "Saturated fatty acids are known drivers of chronic inflammation through TLR4/nfκB-dependent signaling, which is a hallmark of cancers with increased risk." (PMID 32759684, 2020). "This study activated toll-like receptor 4 (TLR4) on MΦs to study how this influence BC behavior because TLR4 has been linked to cancer recurrence." (PMID 30683851, 2019). "TLR4 expression and activation has been shown to correlate with cancer-associated immune dysfunction, enhanced cancer cell survival, cancer progression, and tissue invasion." (PMID 31163699, 2019). "And lncRNA PCAT1 (prostate cancer-associated ncRNA transcript 1)/miR-145-5p/Toll-like receptor 4 (TLR4) signal axis also functions in osteogenic differentiation process." (PMID 31718549, 2019). "Activation of Toll-like receptor 4 (TLR4) promotes the development of colitis-associated cancer through activation of the Cox-2 and EGFR signaling pathway." (PMID 31013961, 2019). "TLR4 signaling pathway induced by LPS can be associated with the survival and proliferation of cancer cells in HCC." (PMID 31340754, 2019). "The anti-inflammatory property is mainly through targeting toll-like receptor 4 signaling pathway, which is also associated with cancer progression." (PMID 31805718, 2019). "Given that TLR4 is expressed in a wide range of cells, it is conceivable that cancer causes systemic disorders by activating TLR4 in many organs." (PMID 31480237, 2019). "CD91 is an eHSP90α receptor on cancer cells and fibroblasts, while TLR4 can associate with HSP90α in LPS-stimulated macrophages." (PMID 31847880, 2019). "Among them, the toll-like receptor 4 (TLR4) signaling pathway is associated with inflammatory response and cancer progression." (PMID 30213077, 2018). "In the current study, a significant reduction in viable cells of both TLR4-deficient cancer cells and mock cells after PTX treatment was found." (PMID 29486738, 2018). "Seven studies, enrolling a total of 713 patients, investigated the association between the DFS of 5 types of cancers and TLR4 expression level." (PMID 29560134, 2018). "Global TLR4 targeting extends our knowledge of the role of this receptor in AT remodeling caused by cancer cachexia." (PMID 30575787, 2018). "After carefully reading the articles, 32 were excluded (10 lacked some important data, 1 used two cut-offs, 18 investigated the role of polymorphism of TLR4 in prognosis of various cancers and 3 only reported odds ratios or relative risks)." (PMID 29560134, 2018). "Toll-like receptor 4 (TLR4) promotes the production of pro-inflammatory cytokines associated with cancer chemoresistance." (PMID 29486738, 2018). "Previous studies have explored the association between toll-like receptor 4 (TLR4) polymorphisms and risk of various cancers, but the results remained controversial." (PMID 29246004, 2017). "TLR4 appears to act as a double-edged sword as it has been linked to both cancer inhibition and growth." (PMID 28572836, 2017).
cancer (continued). "Due to the inconsistence of these findings, arising probably from inadequacy of sample size, we made a comprehensive study to better understand the association between TLR4 gene and cancer risk." (PMID 29246004, 2017). "In this study, we conducted a meta-analysis of 55 independent articles concerning the association between TLR4 polymorphisms and cancer risk." (PMID 29246004, 2017). "Due to the limit of sample size of African population in this study, there is still a requirement of researches including more data for getting insight into association between TLR4 polymorphisms and cancer risk." (PMID 29246004, 2017). "The influence of rs11536889, whose genetic variation contributed to translational regulation of TLR4, possibly by binding to microRNAs, on decrease of cancer risk was also prominent which was consistent with results of previous articles." (PMID 29246004, 2017). "Other pathological pain states as inflammatory neuropathic and cancer pain have been associated with alterations of TLR4 at the spinal cord level." (PMID 27159520, 2016). "Our data are consistent with others studies showing central and peripheral alterations of TLR4 associated with several pathological pain states such as inflammatory, neuropathic and cancer pain." (PMID 27159520, 2016). "Evidence from recent reports suggests that increased expression and activity of TLR4 in chronic infectious and inflammatory conditions is associated with cancer progression." (PMID 25120541, 2014). "The TLR4 single-nucleotide polymorphisms (SNPs), Asp299 and Thr399, have been reported to be involved in inflammation and cancer." (PMID 24959291, 2014). "For example, there were two meta-analyses investigating the correlation between TLR4 +896A/G polymorphism and cancer risk, but the results remained partly conflicting." (PMID 25290654, 2014). "Their meta-analysis indicated that the two SNPs (rs4986790 and rs4986791) in TLR4 were associated with an increased cancer risk, however, one SNP in TLR4 (rs1927911) was associated with a decreased cancer risk." (PMID 24959291, 2014). "The results obtained in our meta-analysis differ from those presented by the other two available meta-analyses addressing the association between TLR4 polymorphisms and risk of cancer." (PMID 23565226, 2013). "Recently, numerous studies have investigated the associations between TLR2 −196 to −174 del and two SNPs of TLR4 (rs4986790 and rs4986791) and the susceptibility to different types of cancer; however, the results remain conflicting." (PMID 24376595, 2013). "In this meta-analysis of 34 independent publications, we found that three genetic variants of TLRs (TLR2 −196 to −174 del, TLR4 rs4986790 and rs4986791) were significantly associated with an increased risk of overall cancers." (PMID 24376595, 2013). "This meta-analysis presented additional evidence for the association between TLR2 and TLR4 polymorphisms and cancer risk." (PMID 24376595, 2013). "Polymorphisms in TLR4 have been extensively studied in several populations in an attempt to find associations with diverse pathologies such as cancer, atherosclerosis and infectious diseases." (PMID 23565226, 2013). "Three more SNPs, namely, rs11536858 (now merged into rs10759931), rs1927911, and rs1927914 of TLR4 gene are also reported to be associated with inflammatory diseases including cancer." (PMID 23936790, 2013). "The aim of this study was to assess the association between TLR2 and TLR4 polymorphisms and cancer risk in a meta-analysis with eligible published studies." (PMID 24376595, 2013). "The remaining three SNPs were rs11536858, rs1927911, and rs1927914 of TLR4 gene and have been shown to be associated with several inflammatory diseases including cancer." (PMID 23936790, 2013). "High expression of TLR4 in HCC tissues was strongly associated with both poor cancer-free survival and overall survival in patients." (PMID 22938142, 2012).
cancer (continued). "Emerging evidence from association investigations has shown that TLR4 polymorphisms are associated with chronic and recurrent inflammation and the occurrence of related cancer." (PMID 21559380, 2011). "We compared our findings on IL-6 and TLR-4 in human tissues with inflammation-tracking in a mouse model of experimentally-induced colitis-associated cancer in Tir8 deficient mice." (PMID 21059221, 2010). "Moreover, TLR-4 is expressed not only in immune cells but also highly in various malignant tumor cells, especially those associated with inflammation." (PMID 40404908, 2025). "UC‐associated cancer tissues exhibit overexpression of TLR4." (PMID 41164267, 2025). "Similarly, Toll-like receptors (TLRs), particularly TLR1, TLR2 and TLR4, have been implicated in cancer development by modulating the tumor microenvironment and promoting inflammatory responses." (PMID 41254241, 2025). "Besides, toll-like receptor signaling pathway involved gene such as TLR4 expression is linked to several cancers." (PMID 38817876, 2024). "In advanced cancer, apoptosis, necrosis, and the release of numerous damage-associated molecular patterns (DAMPs) can induce activation of Toll-like receptor 4 (TLR4) in neutrophils and lead to the release of neutrophil nuclear contents, forming neutrophil extracellular trapping networks (NETs)." (PMID 38842109, 2024). "Active TLR4 signaling, initially identified in breast cancer cells, has been implicated in the chronic inflammation-mediated development of different cancers, cancer progression, chemotherapeutic resistance, cancer cell stemness, invasion, metastasis, and disease relapse." (PMID 38291541, 2024). "This insight into TLR4 function is vital for developing therapeutic strategies targeting diseases, emphasizing the pathway’s significance in understanding and potentially intervening in hyperplasia-associated cancer development." (PMID 38930793, 2024). "It is possible that intracellular MMP9 may be linked to cancer growth, at least in part, by its participation in TLR-4-dependent regulation of innate immunity and inflammation." (PMID 35406619, 2022). "Moreover, the presence of a lymphocytic infiltrate in the surrounding mucosa of cancer samples was associated with increased TLR4 expression." (PMID 35327577, 2022). "Ligustilide could change the immunosuppressive function of cancer-associated fibroblasts (CAFs) through the TLR4-NF-κB pathway and restore T-cell proliferation previously inhibited by the CAF supernatant." (PMID 36408222, 2022). "Fourth, protein kinase C epsilon gene (PRKCE) is overexpressed in most solid tumors and plays critical roles in different cancer-associated pathways, including toll-like receptor 4 (TLR-4) signaling that plays a role in the induction of both innate and adaptive immunity." (PMID 35013211, 2022). "Here, using liquid biopsies from OvCa patients, we demonstrate novel expression of both OR4M1 and TLR4 in cancer-associated circulating cells (CCs) of patients with high grade serous OvCa, with a significant decline in OR4M1 positive cells seen between pre-chemotherapy and treatments." (PMID 36233808, 2022). "TLR4 was also associated with infiltrating immune cell variation and cancer pathway dysregulation." (PMID 36230476, 2022).
cancer (continued). "Moreover, TLR4, being an upstream receptor in the PD-L1 expression and PD-1 checkpoint pathway in cancer, was strongly associated with PD-L1 expression." (PMID 34588497, 2021). "The TLR-4 pathway is strongly implicated in cancer pain hypersensitivity and its attenuation could provide pain relief for cancer patients." (PMID 34638587, 2021). "TLR4 is also associated with infiltrating immune cell variation and cancer pathway dysregulation." (PMID 34141706, 2021). "The M. hyorhinis p37 membrane protein is described to interact with TLR4 and induce the rapid expression of several genes linked to inflammation, in addition to promoting the progression of cancer toward metastasis, as it facilitates PI3k phosphorylation and activation of the PI3k-AKT pathway." (PMID 34949212, 2021). "Indeed, TLR4 is the isoform which is mainly linked to muscle wasting in cancer, being required for LLC-cancer-related muscle wasting." (PMID 33419963, 2021). "There is evidence that TLR4 has multiple associations with cancer." (PMID 34631699, 2021). "Moreover, these p62-deficient cancer cells exhibited marked increases in cell migration and invasion in response to TLR4 stimulation." (PMID 32384667, 2020). "Indeed, miR-216a regulates the crosstalk between cancer cells and the cells of the microenvironment, in particular cancer-associated fibroblasts (CAFs), through regulation of the TLR4/IL6 pathway." (PMID 32230799, 2020). "Another issue to be explored in this study is whether CRBN is involved in autophagy activation induced by TLR4, and implicated in cancer progression." (PMID 31620128, 2019). "Thus, cancer cell-released Hsp70 and Hsp90 cause muscle wasting by activating TLR4 on muscle cells directly, and by activating TLR4 systemically to increase systemic inflammation indirectly." (PMID 31480237, 2019). "Chronic inflammation, caused by dysbiosis, plays a pivotal role in cancer promotion in the liver and colon, tissues known to produce ApoA-I, and inflammatory mechanisms emanating from TLR4 stimulation on cancer cells contribute to malignant growth in this context." (PMID 31374929, 2019). "To identify protein candidates in human cancer cells that can associate with TLR4, we screened human cancer cells using a luciferase assay and three cancer cell lines were selected in which NF-kB activity could be observed." (PMID 30819254, 2019). "Also, an association between TLR2 and TLR4 polymorphisms and cancer risk (particularly for gastric cancer) was shown in previous studies." (PMID 30774831, 2018). "Interestingly, the percentage of cell death was higher in TLR4-deficient cancer cells compared to that of mock cells in both MDA-MB-231 and MDA-MB-435 cells." (PMID 29486738, 2018). "The observed in vivo effects of TLR4 deficiency on cancer cachexia may involve other organs in addition to muscle and immune system." (PMID 28536426, 2017). "In the present work, we further demonstrated that cancer tissue expressed TLR4 level was negatively associated with the OS and DFS in enrolled patients, and more specifically, in TNM stage I and II patients receiving complete pulmonary resection and systematic lymph node dissection." (PMID 28484456, 2017). "Moreover, there is growing evidence that TLR4 activation appears to act as a double-edged sword in cancers, that is, TLR4 activation has been linked to both cancer inhibition and growth." (PMID 28950845, 2017). "Likewise, cancer patients who carry a TLR4 loss-of-function allele relapsed more quickly after chemotherapy than those carrying the normal TLR4 allele." (PMID 26885368, 2016). "However, chronic inflammation related to TLR4 activation remains as a major risk factor in cancer development." (PMID 26883191, 2016). "For instance, LPS could induce epithelial-to-mesenchymal transition (EMT) in cancer cells and has been associated with cancer cell invasion and metastasis in a TLR4 dependent manner." (PMID 27187369, 2016).